INS (insulin)
Diseases named in the same sentence as INS in open-access papers (continued):
Sharing a sentence is not in itself a finding about the gene and the disease.
diabetes (continued). "Diabetes is a metabolic disorder characterized by impaired insulin biological effects or defective insulin secretion, or a combination of both." (PMID 40735644, 2025). "This approach provides higher accuracy and allows more automation in insulin delivery based on continuous glucose monitoring for diabetes management." (PMID 40583499, 2025). "Most demographic and baseline characteristics such as age, BMI, duration of diabetes, and average daily dose of insulin injection showed very small effect sizes, suggesting minimal differences between groups." (PMID 41346986, 2025). "SIRT3 regulates mitochondrial metabolism, insulin resistance, and insulin signaling in diabetes mellitus." (PMID 41304967, 2025). "Univariate Cox regression indicated that age, AMI, diabetes mellitus, heart rate, serum creatinine, cystatin C, eGFR, fibrinogen, bSS, TyG index, LVEF, and the use of diuretics and insulin were significantly associated with the risk of MACEs (all p < 0.05)." (PMID 41295353, 2025). "Multidisciplinary care models that combine individualized insulin therapy, standardized diabetes self-management education, and strong community or outpatient support have demonstrated success in decreasing DKA-related hospital admissions and readmissions." (PMID 41149081, 2025). "In this cohort study of insulin-treated older adults with ADRD and diabetes, CGM use was associated with improved long-term clinical outcomes." (PMID 41329488, 2025). "Diabetes is a chronic metabolic disorder that occurs when the body cannot produce enough insulin (type 1) or cannot effectively use the insulin it does produce (type 2), leading to high levels of glucose (hyperglycemia)." (PMID 41300946, 2025). "Anecdotally, patients with diabetes mellitus after undertaking a liver transplant have reported improved glycaemic control and reduced insulin requirements, compared to other organ transplants where glycaemic control often worsens." (PMID 40664615, 2025). "Shortly after admission, inpatient diabetes teams and/or the outpatient diabetes service should be involved in helping with insulin adjustment and pump settings." (PMID 39432570, 2025). "As previously discussed, diabetes can initially respond to oral antihyperglycemic drugs, but insulin is needed over time in most of the cases." (PMID 41009948, 2025). "Structured diabetes education plays a crucial role in the management of Type 1 Diabetes (T1D), especially with advanced technologies such as continuous subcutaneous insulin infusion (CSII)." (PMID 40887640, 2025). "The liver serves as one of the primary target organs for insulin action and oxidative stress in diabetes." (PMID 41464992, 2025). "The development of diabetes mellitus results from a complex interplay of multiple pathological factors, among which impaired insulin sensitivity and defective pancreatic β-cell function serve as the central pathogenic mechanisms." (PMID 41255531, 2025). "All respondents were receiving diabetes treatment, with the most common methods being diet and exercise (138, 45.25%), insulin therapy (86, 28.20%), and oral medications (59, 19.34%)." (PMID 40734849, 2025). "On the other hand, the retina is a tissue characterized by a high glucose demand, and its function is strongly affected by impaired insulin signaling under pathological conditions such as diabetes." (PMID 41301488, 2025). "The major change in diabetes management that should be implemented once GDM has been identified or in the early stages of pregnancy complicated by T1/2DM is insulin therapy." (PMID 40137145, 2025). "Chronic low-grade inflammation is a critical contributor to the pathogenesis of type 2 diabetes mellitus, acting as a key mediator of insulin resistance and β-cell dysfunction." (PMID 40563357, 2025). "There is compelling evidence linking obstructive sleep apnea (OSA) to Diabetes Mellitus (DM), a group of metabolic diseases marked by elevated blood glucose levels due to defects in insulin secretion and utilization." (PMID 40999017, 2025).
diabetes (continued). "Future research must be adequately powered to assess the effects of various HRT regimens on glycaemic control, insulin sensitivity, and diabetes management in this population." (PMID 41334715, 2025). "The SHAP interpretability analysis further uncovered key predictors of readmission risk, such as prior inpatient admissions, time spent in the hospital, number of medications, and use of specific diabetes medications like insulin." (PMID 40385730, 2025). "Continuous adherence assessment and counselling must be offered to all diabetes mellitus patients on insulin therapy as part of their ambulatory care to help improve outcomes." (PMID 39854487, 2025). "Best practices for managing CFRD include individualised insulin treatment, adjustments during acute illness, and care from a diabetes specialist experienced in diabetes technology and CFRD." (PMID 40430241, 2025). "The application of microneedle technology in diabetes management has been a focal point of research due to the potential advantages microneedles offer over traditional methods of glucose monitoring and insulin delivery." (PMID 39887601, 2025). "After 18 months of ongoing attempts to optimize the insulin regimen and provide intensive diabetes self-management and carbohydrate education, his A1c remained well above his goal at 9.8%." (PMID 40142601, 2025). "Around two-thirds of the participants (64%) were on oral hypoglycaemic drugs (OHD), 9% were on insulin therapy, 19% were on both OHD and insulin, and 9% were advised to change their lifestyle to control Diabetes Mellitus." (PMID 40776998, 2025). "By contrast, diabetes in cats more closely resembles type 2 diabetes and typically develops through a multifactorial interaction between insulin resistance and β-cell dysfunction in the context of obesity, chronic pancreatitis, or other hormonal disorders." (PMID 41472082, 2025). "Regarding the availability of essential drugs to manage diabetes, 0.1% of HFs have glibenclamide, 0.8% have insulin, 0.1% have metformin, and 0.2% have glucose." (PMID 40429492, 2025). "Dietary intervention is a cornerstone of diabetes management, significantly influencing weight control, glycemic regulation, insulin sensitivity, and overall metabolic balance." (PMID 40806442, 2025). "Recent advancements in diabetes therapeutics introduced several novel agents and delivery platforms in human medicine, including long-acting insulin analogs, GLP-1 receptor agonists, and SGLT2 inhibitors." (PMID 41012437, 2025). "Insulin activates the same pro-proliferative signalling pathways as oestrogen; hence, conditions in which insulin is dysregulated, such as diabetes mellitus (DM) and polycystic ovarian syndrome (PCOS), also carry the risk for EC." (PMID 39901248, 2025). "In terms of diabetes management, two‐thirds of respondents reported using oral antidiabetes agents, while 21% were using insulin." (PMID 40818112, 2025). "Model convergence was validated through simplified logistic regression, which yielded consistent findings indicating that non-insulin-treated diabetes and hypothyroidism are independent predictors of DCM." (PMID 41153651, 2025). "Diabetes, a condition marked by insufficient insulin production or utilization, contributes significantly to CKD and other complications like heart failure (HF), another condition influenced by diabetes, obesity and hypertension." (PMID 40176012, 2025). "The daily consumption of flaxseed (13 grams) decreased serum levels of glucose and insulin and increased insulin sensitivity in obese or overweight individuals with pre-diabetes." (PMID 40365191, 2025). "Diabetes represents a persistent metabolic condition marked by increased blood glucose concentrations, which arise from inadequate insulin production, insulin resistance, or a combination of these mechanisms." (PMID 40438395, 2025).
diabetes (continued). "The cost of insulin and diabetes supplies varies according to healthcare system, country, pharmacy, insurance coverage, product tier, and manufacturer rebates." (PMID 41230085, 2025). "Diabetes mellitus (DM) is a complex metabolic disorder characterized by chronic hyperglycemia resulting from defects in insulin secretion and/or action." (PMID 40276644, 2025). "The role of TMAO in diabetes pathology remains controversial; while some studies emphasize its detrimental impact on insulin sensitivity and the progression of diabetes-related complications, others suggest potential protective effects." (PMID 40393987, 2025). "The prevalence of complete remission of T2DM was 20.45%, 19.44%, and 20% at 5, 7, and 9 years respectively, with significant reductions in percentages of patients using diabetes medications or insulin." (PMID 40082386, 2025). "For sensitivity analyses, we used both the insulin demand–adequacy method and the RAD method to evaluate the risk of diabetes in adults (only the adult group had adequate numbers of incident diabetes diagnoses at follow-up)." (PMID 39611962, 2025). "In multivariable analysis, diabetes duration and insulin use were significant predictors, while procedure type was not." (PMID 41231326, 2025). "Literature supporting a role for cDC42 and therefore Pak1 signaling as a critical component of insulin secretion and diseases related to diabetes has been summarized in extensive reviews." (PMID 40065530, 2025). "Many women experienced significant shifts in insulin requirements and glucose levels, leading to emotional exhaustion, a sense of lost control of their diabetes, and concerns regarding the long-term health implications of erratic glycaemia." (PMID 41334715, 2025). "Previous studies have demonstrated that in insulin-treated patients with type 2 diabetes mellitus (T2DM), the use of real-time CGM (rtCGM) can significantly improve glycemic control." (PMID 41141022, 2025). "TWOR-aligned topics (e.g., “insulin,” “glucose,” “obesity”) reflect a clear trend in diabetes research, with increasing prevalence over time." (PMID 40567690, 2025). "Diabetes Mellitus (DM) refers to a group of metabolic disorders characterized by high blood glucose levels resulting from defects in insulin production or action." (PMID 40554560, 2025). "Research shows that quercetin, in rats with STZ induced diabetes, lowered plasma glucose levels and improved glucose tolerance by regenerating pancreatic islets, increasing insulin secretion and improving antioxidant defense." (PMID 41614828, 2025). "For example, basal insulin, often prescribed for diabetes management, affects fasting glycemic control." (PMID 39920712, 2025). "Diabetes mellitus (DM) was defined as fasting plasma glucose ≥ 7.0 mmol/L and/or presence of oral hypoglycaemic or insulin treatment." (PMID 40053071, 2025). "Previous studies have shown that inhibiting adipose tissue lipolysis, including the targeting of ATGL with Atglistatin, in vivo restores systemic insulin sensitivity in rodent models of obesity and diabetes." (PMID 40996861, 2025). "In particular, the development of insulin pumps, advancements in continuous glucose systems, and a wider use of the hybrid closed loop have markedly improved diabetes care in children and adolescents." (PMID 41323155, 2025). "Effective blood sugar management in type 1 diabetes mellitus is accomplished through two or more insulin injections each day." (PMID 40574088, 2025). "The current therapeutic modalities of diabetes, including continuous glucose monitoring and advanced insulin delivery systems, enable tighter diabetes management." (PMID 41227173, 2025). "His diabetes was treated with oral antidiabetics metformin and sulfonylurea, for the first 3 years, and insulin was added to his treatment 3.5 years after diagnosis, and acceptable glycemic control was achieved for 11 years." (PMID 40696585, 2025).
diabetes (continued). "Current therapeutic strategies for diabetes primarily focus on lifestyle interventions, pharmacological treatments (e.g., insulin analogs, metformin), and emerging approaches such as complementary and alternative medicine (CAM)." (PMID 40565658, 2025). "Restoring impaired insulin secretion is a crucial factor in improving glycemic control in patients with type 2 diabetes mellitus." (PMID 40448078, 2025). "Insulin, a pivotal hormone synthesized by the pancreas and regulated through hepatic first-pass metabolism, plays an essential role in the management of diabetes." (PMID 41303503, 2025). "This study shows that Swedish adults with type 2 diabetes on insulin who are using isCGM have a significantly reduced HbA1c and fewer hospital admissions for diabetes-related complications compared with BGM control participants." (PMID 39460755, 2025). "Diabetes mellitus (DM) is a chronic metabolic disorder characterized by hyperglycemia due to impaired insulin secretion, action, or both." (PMID 41141170, 2025). "Diabetes is a chronic disease resulting from the inability of the β-cells of the pancreas to produce a sufficient amount of insulin or failure of the body to effectively utilize the insulin it creates." (PMID 40001488, 2025). "Given the significant impact of pancreatic cancer on patient health, we recommend that pancreatic tumor monitoring should be closely observed during insulin therapy for diabetes to ensure timely detection and management." (PMID 40356973, 2025). "Insulin has played an important role in the treatment of diabetes since its discovery in the early 1920s." (PMID 41531706, 2025). "Out of 2314 models explored, the most effective predictor model included annual net income per person, sex, age, diabetes duration, pre‐isCGM HbA1c, insulin dose/kg, and the interaction between sex and HbA1c." (PMID 39718005, 2025). "Recent evidence suggests that sleep duration and diabetes can be explained by mechanisms such as inflammatory responses, reduced insulin sensitivity, and increased appetite." (PMID 40421240, 2025). "Type 1 diabetes mellitus (T1DM) is a chronic autoimmune disorder characterized by the destruction of insulin-producing pancreatic beta cells, resulting in lifelong insulin dependence." (PMID 40906116, 2025). "These advancements, along with personalized insulin regimens and emerging digital tools, are reshaping the landscape of diabetes care, offering greater flexibility, improved adherence, and better long-term health outcomes." (PMID 40217595, 2025). "A newly diagnosed diabetes patient noticed that physical exercise affected blood sugar levels after being discharged from the hospital, leading her to adjust the insulin dose accordingly." (PMID 40256375, 2025). "Diabetes is a chronic illness that arises from insufficient insulin production by the pancreas or the body's inability to utilize the insulin that is produced." (PMID 40799855, 2025). "Stratified analysis of the relationship between FI-lab and 28-day all-cause mortality was conducted based on factors such as age, gender, race, BMI, insulin use, diabetes, renal disease, liver disease, septic shock, and cirrhosis." (PMID 40265180, 2025). "Diabetes mellitus (DM) is a chronic metabolic disorder characterized by persistent hyperglycemia due to inadequate insulin secretion, insulin resistance, or a combination of both pathophysiological mechanisms." (PMID 40799982, 2025). "The diabetes group showed higher values for age, body mass index, waist circumference, fasting glucose, insulin, HOMA‐IR, systolic blood pressure, triglycerides and prevalence of hypertension." (PMID 40035123, 2025). "Over the last years, metabolic syndromes such as type 2 diabetes mellitus (T2DM), a chronic disorder characterized by hyperglycaemia and alterations in insulin level and/or insulin action, have been identified as risk factors for PD development." (PMID 40676250, 2025).
diabetes (continued). "Diabetes is a common disorder characterized by abnormally high blood sugar (glucose) levels due to insufficient insulin production or utilization." (PMID 41345203, 2025). "Galectin-3, a β-galactoside-binding lectin, is upregulated in several metabolic disorders, such as obesity and diabetes, by disrupting the insulin signaling pathways in insulin-responsive organs, therefore playing a role in the pathogenesis of T2DM." (PMID 40004572, 2025). "On the other hand, FXR activation by specific agonists suppresses bile acid and fatty acid synthesis and increases glucose and insulin sensitivity in murine models with obesity and diabetes." (PMID 40507175, 2025). "In the following month, the patient developed a post-transplantation diabetes mellitus, which was initially managed with insulin and currently treated solely with a GLP-1 receptor agonist." (PMID 40491591, 2025). "Articles were selected based on studies conducted on human participants diagnosed with type 2 diabetes mellitus, involving structured exercise interventions, and reporting at least one outcome related to insulin function or glycemic control." (PMID 41295324, 2025). "Although clinical and epidemiologic studies have linked diabetes with increased HNSCC incidence and poorer prognoses, the specific connection between insulin signaling and glucose-fueled redox metabolism in HNSCC remains largely unexplored." (PMID 40371988, 2025). "Type 1 diabetes mellitus (T1DM) results from autoimmune destruction of pancreatic β-cells, resulting in absolute insulin deficiency, necessitating exogenous insulin therapy for glycaemic control." (PMID 39982365, 2025). "Insulin resistance, a central factor in the pathogenesis of type 2 diabetes mellitus, can be effectively prevented or mitigated by improving insulin sensitivity through lifestyle modifications or the pharmacological use of insulin sensitizers." (PMID 39950117, 2025). "Clinical predictors were BMI (β = 0.006, p = 0.045), diabetes duration >10 years (β = 0.094, p = 0.009), and insulin use (β = 0.121, p = 0.003) (Adjusted R2 = 0.319)." (PMID 41008733, 2025). "Type 2 diabetes mellitus (T2DM) is a chronic metabolic condition characterized by high blood glucose levels, insulin resistance, and a relative deficiency in insulin." (PMID 41009460, 2025). "Regarding insulin levels, the D group showed a significant increase in insulin levels compared to the non-diabetes group (p < 0.001)." (PMID 40362714, 2025). "In the HFD/STZ-induced diabetic mice model, 4-VG effectively alleviated the symptoms of hyperglycemia and improved lipid metabolism via activating the insulin signaling pathway." (PMID 41154025, 2025). "Diabetes mellitus (DM) is a systemic metabolic disorder characterized by chronic hyperglycemia resulting from insulin secretion defects and/or insulin resistance." (PMID 41208872, 2025). "Mitochondrial respiration and insulin secretion are altered under pathological conditions where beta cell mass is limited, including diabetes and islet transplantation." (PMID 40133488, 2025). "This multidisciplinary approach aimed to address both insulin sensitivity and weight-related metabolic factors, as supported by findings from recent diabetes remission trials." (PMID 40656273, 2025). "While diabetes-related vessel abnormalities in insulin-sensitive tissues have been well documented, the impact of obesity on islet vessels remains relatively unappreciated, with existing knowledge mostly limited to morphological characterizations." (PMID 40488531, 2025). "Diabetes is a chronic illness that arises from either insufficient insulin production or inefficient insulin utilization by the body." (PMID 40277563, 2025). "Generally, the main therapies of diabetes mellitus are glucose controlling drugs and insulin injection." (PMID 39687469, 2025).